ABR (ABR activator of RhoGEF and GTPase)
Description:
Protein with a unique structure having two opposing regulatory activities toward small GTP-binding proteins. The C-terminus is a GTPase-activating protein domain which stimulates GTP hydrolysis by RAC1, RAC2 and CDC42. Accelerates the intrinsic rate of GTP hydrolysis of RAC1 or CDC42, leading to down-regulation of the active GTP-bound form. The central Dbl homology (DH) domain functions as a guanine nucleotide exchange factor (GEF) that modulates the GTPases CDC42, RHOA and RAC1. Promotes the conversion of CDC42, RHOA and RAC1 from the GDP-bound to the GTP-bound form. Functions as an important negative regulator of neuronal RAC1 activity (By similarity). Regulates macrophage functions such as CSF-1 directed motility and phagocytosis through the modulation of RAC1 activity (By similarity).
Synonyms: MDB
Tractability: PROTAC: ubiquitination databases record sites on it; its protein half-life has been measured.
Gene: Protein-coding gene on chromosome 17 (1,003,519 to 1,229,738, reverse strand). Ensembl gene ENSG00000159842.
Subcellular location: Cell projection, dendritic spine; Cell projection, axon; Synapse
Subcellular location (Human Protein Atlas): Cytosol; Nucleoplasm
Pathways (Reactome):
Signal Transduction: CDC42 GTPase cycle; G alpha (12/13) signalling events; NRAGE signals death through JNK; RAC1 GTPase cycle; RAC2 GTPase cycle; RAC3 GTPase cycle; RHOA GTPase cycle; RHOB GTPase cycle; RHOC GTPase cycle
Gene Ontology:
Molecular function: GTPase activator activity; guanyl-nucleotide exchange factor activity; protein binding
Biological process: activation of GTPase activity; modulation of chemical synaptic transmission; regulation of small GTPase mediated signal transduction; small GTPase-mediated signal transduction; intracellular signal transduction; signal transduction
Cellular component: membrane; cytosol; glutamatergic synapse; Schaffer collateral - CA1 synapse; synapse; axon; dendritic spine
Genetic constraint (gnomAD): Loss-of-function variants: 35 observed, 107.63 expected, observed/expected ratio (o/e) 0.33, 90% interval 0.25 to 0.43. The upper end of that interval is the gene's LOEUF score, 0.43, which puts it in group 1 of 6, group 1 being the genes least tolerant of losing a copy. Missense variants: 815 observed, 1,123.7 expected, observed/expected ratio (o/e) 0.73, 90% interval 0.68 to 0.77. Synonymous variants: 498 observed, 468.94 expected, observed/expected ratio (o/e) 1.06, 90% interval 0.99 to 1.14.
Homologues: Orthologues: guinea pig ABR (99% identical), macaque ABR (98% identical), pig ABR (97% identical), dog ABR (97% identical), rabbit ABR (97% identical), mouse Abr (97% identical), rat Abr (97% identical), tropical clawed frog abr (83% identical), chimpanzee ABR (80% identical), zebrafish ABR (46% identical), Drosophila melanogaster RhoGAP1A (33% identical), zebrafish abr (31% identical). Paralogues in human: BCR (67% identical).
Diseases named in the same sentence as ABR in open-access papers:
ABR is named in the same sentence as 10 diseases in open-access papers, as found by Europe PMC text mining. Sharing a sentence is not in itself a finding about the gene and the disease. The quoted sentences say what the papers report.
brain neoplasm (1 paper, 2018). A neoplasm (disease) that involves the brain. "This analysis identified neoplasms and nervous system diseases as the most associated diseases with the TRPV2 interactome, and highlighted a set of genes previously associated to brain neoplasms, such as: ABR, FGF1, KCNJ10, PEBP1, PLP1, SDC3 and TRPV2." (PMID 29719613, 2018). "The TRPV2 interactome showed a high association with early glia-related neoplasms, especially glioma/glioblastoma, being ABR, FGF1, KCNJ10, PEBP1, PLP1, SDC3, and TRPV2, the genes associated to these brain neoplasms." (PMID 29719613, 2018).
neoplasm (3 papers, 2018 to 2021). A benign or malignant tissue growth resulting from uncontrolled cell proliferation. "KALRN, MCF2/Dbl, NGEF/EPHEXIN, ARHGEF7/βPix/COOL-1, CDC42EP2, DOCK9, NET1, TIAM2, ABR, PLEKHG5, RhoBTB2 and PREX1 were identified as being increased at the tumour rim." (PMID 33256106, 2020).
cancer (2 papers, 2021). A tumor composed of atypical neoplastic, often pleomorphic cells that invade other tissues. "In addition, NSCLC subgroups with higher nodal metastasis levels or cancer stages generally have lower median expression of ABR, PREX1, DOCK2, and DOCK4, whereas statistical significance for the comparison among these subgroups remains to be verified with a larger number of samples." (PMID 34783629, 2021).
infection (1 paper, 2016). The state of being infected such as from the introduction of a foreign agent such as serum, vaccine, antigenic substance or organism. "As AbR genes disseminate mostly by conjugation, we proposed a new strategy to control AbR dissemination before infection, targeting AbR plasmid conjugation." (PMID 26812051, 2016).
ABR also shares sentences with these, for which no sentence is quoted: bacterial infection (1 paper); glioblastoma (1); glioma (1); lung carcinoma (1); nervous system diseases (1); ovarian carcinoma (1).